KLHL14 (kelch like family member 14)
Synonyms: KIAA1384
Tractability: No criterion of Open Targets' tractability assessment is met for any kind of drug.
Gene: Protein-coding gene on chromosome 18 (32,672,601 to 32,773,023, reverse strand). Ensembl gene ENSG00000197705.
Subcellular location: Cytoplasm, cytosol; Endoplasmic reticulum membrane
Subcellular location (Human Protein Atlas): Cytosol; Actin filaments
Gene Ontology:
Biological process: proteasome-mediated ubiquitin-dependent protein catabolic process
Cellular component: cytosol; endoplasmic reticulum; Cul3-RING ubiquitin ligase complex; neuron projection; neuronal cell body; endoplasmic reticulum membrane
Genetic constraint (gnomAD): Loss-of-function variants: 20 observed, 52.88 expected, observed/expected ratio (o/e) 0.38, 90% interval 0.26 to 0.55. The upper end of that interval is the gene's LOEUF score, 0.55, which puts it in group 2 of 6, group 1 being the genes least tolerant of losing a copy. Missense variants: 597 observed, 721.28 expected, observed/expected ratio (o/e) 0.83, 90% interval 0.77 to 0.89. Synonymous variants: 294 observed, 310.62 expected, observed/expected ratio (o/e) 0.95, 90% interval 0.86 to 1.04.
Homologues: Orthologues: chimpanzee KLHL14 (100% identical), dog KLHL14 (99% identical), rabbit KLHL14 (99% identical), mouse Klhl14 (99% identical), pig KLHL14 (99% identical), rat Klhl14 (99% identical), guinea pig KLHL14 (99% identical), macaque KLHL14 (94% identical), tropical clawed frog klhl14 (93% identical), zebrafish klhl14 (88% identical). Paralogues in human: KLHL13 (32% identical), KLHL9 (32% identical), KLHL31 (31% identical), KLHL26 (30% identical), KLHL36 (29% identical), KLHL34 (28% identical), KLHL32 (28% identical), KLHL22 (27% identical), KLHL4 (27% identical), KLHL1 (27% identical), KLHL5 (27% identical), KLHL28 (27% identical), and 42 more.
Diseases named in the same sentence as KLHL14 in open-access papers:
KLHL14 is named in the same sentence as 28 diseases in open-access papers, as found by Europe PMC text mining. Sharing a sentence is not in itself a finding about the gene and the disease. The quoted sentences say what the papers report.
diffuse large B-cell lymphoma (4 papers, 2022 to 2024). "Subsequently, KLHL14 has also been reported to act either as a tumor promoter, in ovarian and endometrial cancers, or a tumor suppressor, in a subtype of diffuse large B cell lymphoma." (PMID 39124679, 2024). "Recently, also KLHL14 has been shown to function as tumor suppressor in diffuse large B-cell lymphoma and in malignant mesothelioma." (PMID 38909024, 2024).
endometrial cancer (4 papers, 2020 to 2024). Primary or metastatic malignant neoplasm involving the endometrium (mucous membrane that lines the endometrial cavity). "Two manuscripts reported an association between KLHL14 and increased tumor proliferation and migration in ovarian and endometrial cancer." (PMID 38509883, 2024). "Previous studies demonstrated that KLHL14 was over-expressed in B cells, ovarian and endometrial cancers." (PMID 38509883, 2024). "KRTCAP3 was reported to be overexpressed in gastric cancer and human keratinocytes, while KLHL14 participated in the development and metastasis of endometrial cancer." (PMID 32716025, 2020).
ovarian carcinoma (4 papers, 2016 to 2025). A malignant neoplasm originating from the surface ovarian epithelium. "In ovarian cancer, the increased expression of the KLHL14 gene is associated with a poorer prognosis." (PMID 41465326, 2025). "Overall, our results indicated that KLHL14 can function as a biomarker for ovarian cancer and provide novel insights into the mechanisms underlying the microenvironment of serous ovarian cancer." (PMID 36046368, 2022). "Additional analysis of the mechanisms underlying the association between high expression levels of KLHL14 and ovarian cancer were conducted using pathway analysis, immune cell infiltration analysis, functional analysis, and half-maximal inhibitory concentration (IC50) analysis." (PMID 36046368, 2022). "In another study, KLHL14 was found to be a predictive factor of poor prognosis in patients with ovarian cancer and a target for early detection." (PMID 36568181, 2022). "We analysed KLHL14 expression levels in different types of human cancers, and we observed that KLHL14 was significantly upregulated in ovarian cancer compared to that in other kinds of human cancers." (PMID 36046368, 2022). "KLHL14 is anticipated to emerge as a novel molecular marker specifically for ovarian carcinoma." (PMID 36046368, 2022). "A significant level of KLHL14 expression was observed in ovarian cancer patients at all stages." (PMID 36568181, 2022). "Moreover, compared with normal tissues, OV tissues obtained from patients in all stages of ovarian cancer showed the KLHL14 overexpression." (PMID 36046368, 2022). "An increase in the KLHL14 expression indicates a poor prognosis in patients with ovarian cancer." (PMID 36046368, 2022). "In our results we found that KLHL14 was enriched in HGSC, however there are currently no studies characterizing the function of this gene product in ovarian cancer." (PMID 27713570, 2016).
lymphoma (3 papers, 2022 to 2024). A malignant (clonal) proliferation of B- lymphocytes or T- lymphocytes which involves the lymph nodes, bone marrow and/or extranodal sites. "Regarding the distribution, KLHL14 mutations were mainly (10% of the cases) found in adenomas and adenocarcinomas, followed by lymphoma (8.51% of the cases) and melanoma (5.96% of the cases)." (PMID 39124679, 2024). "Moreover, KLHL14 (Kelch-Like Family Member 14, a tumor-suppressing chaperone regulating protein folding, frequently mutated in lymphomas) promotes CD79a and CD79b ubiquitination and their consequent downregulation." (PMID 38203179, 2023). "Furthermore, lymphoma sequencing studies revealed that the network of concurrently mutated genes in MCD DLBCL cluster includes inactivating mutations of KLHL14, which promotes My-T-BCR-dependent NF-κB signaling via reduction of CD79a and CD79b ubiquitination." (PMID 38203179, 2023). "Finally, we explored the potential pathways that are closely associated with KLHL14, the results revealed that KLHL14 is highly correlated with lymphoma." (PMID 36568181, 2022).
malignant mesothelioma (3 papers, 2024). A malignant neoplasm of the pleura or peritoneum, arising from mesothelial cells. "It has recently been shown that KLHL14 anti-oncogenic action in malignant mesothelioma is linked to changes in its nuclear-cytoplasmic shuttling in response to oncogenic stimuli." (PMID 38909024, 2024). "Then, it was demonstrated that KLHL14 possesses an anti-oncogenic action due to its ability to inhibit cell proliferation, migration, invasion, colony formation and EMT in malignant mesothelioma (MM)." (PMID 39124679, 2024).
CNS lymphomas (2 papers, 2020 to 2024). "Besides, KLHL14 was also found to mutate in primary central nervous system lymphoma (PCNSL), playing a role in CNS development." (PMID 32716025, 2020).
MALT lymphoma (2 papers, 2022 to 2023). An indolent, extranodal type of non-Hodgkin lymphoma composed of small B-lymphocytes (centrocyte-like cells). "In another study, an online database provided a rationale for mRNA vaccine development and suggested that KLHL14 might serve as an antigen for the development of mRNA vaccines in MALT lymphoma patients." (PMID 37234985, 2023). "In this study, we provide a theoretical foundation for the development of mRNA vaccines and suggest that KLHL14 could potentially be used as antigens to develop mRNA vaccines for MALT lymphoma." (PMID 36568181, 2022).
anaplastic thyroid cancers (1 paper, 2024). "Here we show that KLHL14 expression is strongly reduced in anaplastic thyroid cancer, the less differentiated and most aggressive type of thyroid neoplasia." (PMID 38909024, 2024). "To investigate the possible involvement of Klhl14 in thyroid neoplastic transformation we compared its expression in samples of human anaplastic thyroid cancers (ATC), papillary thyroid cancers (PTC) and normal tissue, employing GEO2R software to explore two publicly available datasets." (PMID 38909024, 2024).
brain tumor (1 paper, 2024). "Only in 0.78% of the cases were KLHL14 mutations found in brain tumors; specifically, in lower grade glioma." (PMID 39124679, 2024). "Finally, the distribution of KLHL14 mutations was evaluated in 155 cases of brain tumor along with a relative overall survival plot." (PMID 39124679, 2024).
glioma (1 paper, 2024). A benign or malignant brain and spinal cord tumor that arises from glial cells (astrocytes, oligodendrocytes, ependymal cells). "Subsequently, based on the TGCA results, NOD/SCID mouse xenografts of both human glioma and lung adenocarcinoma were used to detect the nuclear protein domain specificity of KLHL14 and E-Cad antibodies." (PMID 39124679, 2024).
mesothelioma (1 paper, 2024). A usually malignant and aggressive neoplasm of the mesothelium which is often associated with exposure to asbestos. "•KLHL14 is expressed in mesothelioma subtypes-derived cells." (PMID 38509883, 2024).
osteoarthritis (1 paper, 2025). A noninflammatory degenerative joint disease occurring chiefly in older persons, characterized by degeneration of the articular cartilage, hypertrophy of bone at the margins and changes in the synovial membrane. "Specifically, ZNF25 was suggested as a candidate gene for osteoblast differentiation in humans, KLHL14 as a candidate gene for bone strength in chicken, and ATP9B as a candidate gene regulating the progression of osteoarthritis." (PMID 40965274, 2025).
pleural mesothelioma (1 paper, 2024). A neoplasm that arises from the mesothelial cells of the pleura. "Thus, we initially evaluated KLHL14 expression in the three subtypes (epithelioid, biphasic and sarcomatoid) of pleural mesothelioma by interrogating cBioPortal database." (PMID 38509883, 2024).
thyroid (1 paper, 2024). "In this paper we show that the E3 ubiquitin ligase component KLHL14 is strongly reduced in human and in vivo experimental undifferentiated thyroid cancer and is able to reduce proliferation and survival in thyroid neoplastic cells in vitro." (PMID 38909024, 2024). "To establish if Klhl14 reduction plays a functional role in cancer, we tested if Klhl14 ectopic expression in thyroid neoplastic cells could interfere with the transformed phenotype." (PMID 38909024, 2024). "Analysis of Klhl14 promoter shows that its activity dramatically falls down in thyroid cells upon Ras oncogenic activation, suggesting that its transcriptional repression could represent an early event in thyroid neoplastic transformation." (PMID 38909024, 2024). "The possibility that also KLHL14, representing a marker of thyroid follicular cells since their commitment, could be involved in thyroid neoplastic transformation has not been explored yet." (PMID 38909024, 2024).
thyroid cancer (1 paper, 2024). "Similarly, KLHL14 was found to also act as a tumor suppressor in thyroid cancer, where it impairs cell growth, alters the expression of key thyroid differentiation markers and increases apoptosis in thyroid neoplastic cells." (PMID 39124679, 2024). "However, clear nuclear expression of KLHL14 was reported in MM and thyroid cancer as well as in other cell lines." (PMID 39124679, 2024).
tumor (11 papers, 2021 to 2025). "Correspondingly, mutation frequencies of the KLHL14 gene among the 43 patients with primary tumor tissue samples revealed a similar trend, although the difference was not significant (p = 0.064), possibly due to a limited sample size." (PMID 36280874, 2022). "Furthermore, the nuclear localization of KLHL14 was significantly associated with higher tumor invasiveness grades." (PMID 39124679, 2024). "Based on the prognostic prediction model and the tumor mutation analysis, we discovered that KLHL14 may play an important role in DLBCL cohort." (PMID 36568181, 2022). "Further analysis, including pathway analysis and immune cell infiltration studies, suggests that KLHL14 plays a role in the tumor microenvironment and has potential as a therapeutic target." (PMID 41465326, 2025). "Surprisingly, the contemporary immunostaining for KLHL14 and E-Cad in the xenografted tumor explants revealed the co-localization of these two proteins in both nuclear and cytoplasmic compartments." (PMID 39124679, 2024). "KLHL14 is a poorly characterized protein belonging to the Kelch-like family, which is involved in the regulation of cell morphology and ubiquitination, and plays a crucial role in disease and tumor development." (PMID 38509883, 2024). "Actually, there is very limited literature on KLHL14 action and its association with TGF-β/EMT signaling pathway, but data on other KLHL proteins have demonstrated correlations with a variety of cellular processes involved in tumor development and metastasis." (PMID 38509883, 2024). "Notably, this co-localization was sensibly increased in the most invasive forms of this tumor, thus confirming a correlation of the gravity of NF-PitNETs with the nuclear translocation of KLHL14/E-Cad." (PMID 39124679, 2024). "In addition, our results support the fact that KLHL14 may function as a tumor suppressor in MM." (PMID 38509883, 2024). "Among them, BNC2, SYNM, and TCF21 target genes were detected in all tumor locations, and three targets (GRIK2, KLHL14, and MS4A2) were shared by R-CRC and L-CRC but not by RC." (PMID 37987361, 2023).
cancer (6 papers, 2018 to 2025). A tumor composed of atypical neoplastic, often pleomorphic cells that invade other tissues. "Preliminarily, the analysis of KLHL14 mutations’ involvement in different types of cancer was performed by using the TCGA portal." (PMID 39124679, 2024). "The E-Cad and KLHL14 antibodies were tested on sections of both healthy and cancer tissues for single and double IHC reaction." (PMID 39124679, 2024). "Such reduction of Klhl14 in different experimental cancer models developed in different species further strengthens the original in silico observation." (PMID 38909024, 2024). "Subsequently, other research groups analyzed KLHL14 functions in different cancer and non-cancer cells, in particular B cells and neurons." (PMID 38509883, 2024). "More recently, KLHL14 was reported to be involved in different human cancers." (PMID 38909024, 2024). "Our results showed that the KLHL14 gene is overexpressed in some cancers." (PMID 36046368, 2022). "Thyroids from treated and control mice were analyzed for Klhl14 mRNA expression both by in situ hybridization (ISH) and RT-PCR showing a severe decrease of Klhl14 levels in induced cancers respect to that observed in the control samples." (PMID 38909024, 2024). "The Cancer Genome Atlas (TCGA) and the Gene Expression Profiling Interactive Analysis (GEPIA) databases were used to determine the function of KLHL14 in anticipating overall survival (OS)." (PMID 36046368, 2022). "Eight of these had decreased expression in cancer (KLHL3, KLHL4, KLHL13, KLHL14, KLHL29, KLHL30, KLHL32, and KLHL33) while four genes (ENC1, KLHL12, KLHL17, and KLHL35) had patterns of up-regulated gene expression." (PMID 30647843, 2018). "Finally, we demonstrated that in other cancer cells lines (A549, Caco-2 and HEK-293T), KLHL14 showed both cytoplasmic and nuclear expression, with prevalent nuclear localization observed in HEK-293T and Caco-2 cells too." (PMID 38509883, 2024). "KLHLs with significant hazard ratios or inverse hazard ratios for four cancer types regardless of direction were KLHL14, KLHL22, KLHL29, KLHL32, and KLHL36." (PMID 30647843, 2018).
KLHL14 also shares sentences with these, for which no sentence is quoted: adenocarcinoma (1 paper); adenoma (1); B-cell lymphoma (1); gastric cancer (1); kidney chromophobe (1); lung adenocarcinoma (1); lymphoid neoplasm (1); melanoma (1); ovarian serous cystadenocarcinoma (1); papillary thyroid cancers (1); uterine corpus endometrial carcinoma (1).